LEP (leptin)
Diseases named in the same sentence as LEP in open-access papers (continued):
Sharing a sentence is not in itself a finding about the gene and the disease.
Obesity (continued). "This is in line with recent observations showing that, on an already potent obesity-inducing hypercaloric diet, fructose induces leptin-resistance leading to pronounced susceptibility to increased weight gain." (PMID 19956534, 2009). "Taken together with previous reports in rodent models as well as humans, data presented herein demonstrate the potential role for leptin in the inflammatory process associated with obesity." (PMID 20150963, 2009). "On the other hand, a decrease in CL formation together with weight gain is suggestive of obesity-associated changes, such as hyperleptinemia followed by leptin resistance or disturbed androgen levels with ovarian dysregulation." (PMID 19309531, 2009). "For example, decreased leptin transport is associated with peripheral leptin resistance in obesity and decreased efflux of amyloid beta protein is associated with Alzheimer's disease." (PMID 19534732, 2009). "Increased levels of leptin have been shown to correlate with obesity, a known risk factor for postmenopausal breast cancer." (PMID 19208204, 2009). "The highly polymorphic Leptin tetranucleotide locus is located in 476 bp 3' of exon 3 of leptin gene and has been associated with obesity and hypertension." (PMID 19772655, 2009). "Since obesity and hyperleptinemia are also associated with the hepatic disease known as nonalcoholic steatohepatitis, we next determined if leptin administration promotes hepatic inflammation." (PMID 20150963, 2009). "Several researchers reported the evidence of linkage and/or association between variation in the Leptin gene region and traits related to obesity." (PMID 19772655, 2009). "Obesity is pathogenically associated with the occurrence of leptin resistance in human as well as in animal models." (PMID 19727392, 2009). "Murine obesity models included genetically leptin-deficient ob/ob mice and wild type (WT) mice fed a high fat diet (HFD), that were compared to their lean counterparts." (PMID 19513120, 2009). "For example, transgenic mice overexpressing leptin exhibit adult-onset obesity, and they are more susceptible to diet-induced obesity because of increased leptin secretion." (PMID 19750222, 2009). "Further, the obesity-induced changes which occur in the daily expression of feeding peptides, such as increased leptin levels, are more likely to be associated with alterations in peripheral rather than either SCN or MBH oscillators." (PMID 19712475, 2009). "Nevertheless, the cyclic AMP (cAMP) responsive element-binding protein-1 (CREB1) is expressed in the VMH, and CREB1−/− mice exhibit adult onset obesity associated with hyperphagia, elevated insulin and leptin levels, as well as leptin resistance." (PMID 19750222, 2009). "Increased visceral and subcutaneous adiposity is known to cause higher levels of serum leptin, the hallmark of human obesity, and hyperinsulinaemia, both of which have been linked to ventricular hypertrophy in humans and in animal models." (PMID 19393079, 2009). "Increased circulating levels of leptin (i.e. hyperleptinemia) have been found to be associated with obesity induced by overnutrition, as in the case of chronic intake of high-fat diet." (PMID 19727392, 2009). "The challenge is to develop diagnostic approaches for the different forms of central leptin resistance and design personalized healthcare programs to treat obesity." (PMID 19878575, 2009). "It is worth noting that the association between plasma leptin concentrations and breast cancer risk remained after adjustment for obesity indices in this study." (PMID 19223908, 2009). "Left ventricular mass was then compared to serum and anthropometric markers of obesity linked to left ventricular mass, i.e. height, age, blood pressure, total fat mass, visceral fat mass, lean mass, serum leptin and fasting insulin level." (PMID 19393079, 2009).
Obesity (continued). "Mutations in the gene encoding leptin are reported to cause severe obesity in animal models and humans indicating a direct relationship between leptin and obesity." (PMID 19772655, 2009). "With respect to breast cancer, and obesity, leptin has been an adipokine implicated in mammary tumorigenesis." (PMID 18182989, 2008). "Among mice that are leptin-deficient (ob/ob) or leptin-resistant (db/db), hyperphagia is a constant and obesity, a hallmark." (PMID 18769731, 2008). "Crossbreeding the hIAPP mice with leptin-deficientObese mice introduced more severe obesity and insulin resistance ascompared to the high-fat diet." (PMID 18497871, 2008). "Obesity is associated with high levels of adiposity, significantly increased levels of adipokines such as leptin and elevated levels of the inflammatory marker C-reactive protein (CRP)." (PMID 18275595, 2008). "It has been described that obesity, leptin and adiponectin are related with the risk of some types of cancer such as that of the breast, endometrium, colon and prostate." (PMID 21566743, 2008). "It is noteworthy that mutations affecting leptin exist in humans, but with inconstant phenotypic manifestations in terms of obesity." (PMID 18489748, 2008). "We have previously shown that progressive obesity in aging LY mice is associated with a concomitant diminution in ovarian function, which is paralleled by acquired insulin and leptin resistance." (PMID 18348723, 2008). "The relationship between obesity, leptin and endometrial cancer risk have been observed in clinical studies." (PMID 21566743, 2008). "In sharp contrast to leptin, plasma adiponectin levels are negatively correlated with body fat, decreasing with obesity and increasing in response to weight loss." (PMID 17448988, 2007). "Recently, metabolic factors related to obesity, such as secretion of leptin, have been linked with the onset and progression of OA." (PMID 17589595, 2007). "The association of leptin to waist circumference (a surrogate for upper body obesity) and hip circumference confirms findings in Mexican American populations." (PMID 17617917, 2007). "Leptin is suggested to increase insulin sensitivity or to cause insulin resistance and obesity is associated with leptin resistance and a decreased transport of leptin across the blood-brain barrier." (PMID 17311679, 2007). "Short sleep duration has been shown to be a risk factor for obesity in children, through the modulation of hormones such as leptin and ghrelin, the reduced levels of which can increase hunger and appetite and influence weight gain." (PMID 17880729, 2007). "Another important focus of current research is the association between obesity-linked leptin resistance and the development of neurodegenerative disorders such as Alzheimer's disease." (PMID 18024215, 2007). "For example among Taiwanese aboriginal populations, greater incidences of obesity were associated with the G-2548A polymorphism in the promoter region of the leptin gene and the Gln223Arg (Q223R) polymorphism of the leptin receptor gene." (PMID 16942616, 2006). "Obesity is associated with higher circulating levels of leptin, and leptin has angiogenic activity that correlates with metastasis." (PMID 16465189, 2006). "Previous studies have provided evidence for the association of leptin with key variables of the metabolic syndrome and with insulin sensitivity, independently of obesity." (PMID 16669997, 2006). "This difference in effect together with the observation that most obese humans have high levels of leptin suggest that leptin resistance causes human obesity." (PMID 16336696, 2005). "For example, the Leprdb and Lepob-TGFα transgenic mouse model, used to investigate the effects of obesity on tumorigenesis, are leptin deficient or have a leptin receptor defect." (PMID 16168107, 2005).
Obesity (continued). "The researchers also found that shorter sleep times were associated with increased circulating ghrelin and decreased leptin, a hormonal pattern that is consistent with decreased energy expenditure and increased appetite and obesity." (PMID 15599390, 2004). "Circulating leptin appears to be one of thebest biological markers of obesity and that hyperleptinemiais closely associated with several metabolicrisk factors related to insulin resistance in thediabesity syndrome." (PMID 12369710, 2001). "These processes contribute to the development and amplification of central insulin and leptin resistance, which may represent both predisposing factors for obesity and downstream consequences of chronic metabolic dysregulation." (PMID 41596611, 2026). "We further posited that TRIB1 could facilitate C/EBPα ubiquitination, reduce leptin synthesis, and alleviate mitochondrial fragmentation associated with DRP1 activity, thereby improving leptin signaling and mitochondrial function in obesity." (PMID 41588470, 2026). "Leptin is a key adipokine that circulates in proportion to increased body fat in common obesity and is involved in both appetite regulation and chronic mild inflammation associated with obesity." (PMID 41528263, 2026). "Reported outcomes included improvements in insulin sensitivity, regulation of leptin levels, and modulation of the gut-brain axis, which may collectively contribute to a reduced risk of obesity." (PMID 41754191, 2026). "Amplified leptin levels are associated with the risk of diabetes or obesity." (PMID 41549047, 2026). "The failure of hyperleptinemia to decrease adiposity in common forms of obesity has led to the notion that impaired leptin receptor (LepRb) signaling ("leptin resistance") might cause obesity." (PMID 42082152, 2026). "As a biomarker, leptin may capture obesity‐related vascular risk beyond BMI, though routine testing is rare and interpretation must consider sex differences." (PMID 41567175, 2026). "Overweight and obesity increased adiposity may enhance a proinflammatory microenvironment through increased production of adipokines such as leptin, visfatin, and resistin, which have been linked to elevated CRP, TNF-α, and IL-6 levels." (PMID 41517610, 2026). "On the other hand, it is known that obesity is associated to central resistance to leptin." (PMID 41240372, 2026). "Indeed, nearly all known monogenic sources of human obesity arise from mutations in what subsequently emerged as a leptin-melanocortin signaling pathway that controls food intake." (PMID 40427545, 2025). "Administration of leptin has been shown to prevent obesity in individuals with this deficiency." (PMID 40019662, 2025). "Changes in endogenous cannabinoids (eCBs) signaling strength are inversely related to energy state, where impaired synthesis of 2-AG in MC4R neurons leads to weight loss, increased serum leptin sensitivity, reduced appetite, increased energy expenditure, and resistance to diet-induced obesity." (PMID 40130157, 2025). "Moreover, research has revealed metabolic disorders caused by mutations in the leptin gene (ob), particularly obesity, thermogenesis, and lipolysis defects, which are closely related to the reduced sympathetic innervation of adipose tissue." (PMID 40452923, 2025). "Leptin has been observed to have both beneficial and detrimental effects on neurons, contingent on the context, and its imbalance in obesity may be linked to neurodegenerative processes in MS." (PMID 40951582, 2025). "Previous research has shown that obesity is associated with increased serum leptin levels, which may disrupt hypothalamic secretion of thyrotropin-releasing hormone, leading to elevated TSH levels." (PMID 40692879, 2025). "Furthermore, obesity induced by either a high-fat diet or by genetic deletion of the Lep gene (encoding leptin) compromises the host immune responses to H1N1 IAV infection." (PMID 40799653, 2025).
Obesity (continued). "Either resistance to leptin action in specific tissues or excessive leptin activity, associated with obesity-related hyperleptinemia, may cause metabolic and inflammatory damage." (PMID 40283443, 2025). "Moreover, our previously published reports exploring the associations between obesity, leptin, NT‐proBNP and incident HF,39, 40 have used the same diagnostic method for incident HF." (PMID 40118794, 2025). "Similarly, genes linked to obesity, leptin, MTHFR, and serotonin receptor 2C are implicated in both MetS and schizophrenia." (PMID 39834212, 2025). "To investigate whether different energy statuses affect the response to SGLT2i, we investigated the metabolic effects of dapagliflozin in lean and a genetic model of obesity represented by ob/ob leptin-deficient mice." (PMID 40059147, 2025). "To reveal the underlying mechanism behind the lack of weight gain in p38αSFTPC-homo mice fed with a HF-Dox–supplemented diet, we monitored the levels of leptin and adiponectin, critical adipokines suggested to play opposing roles in obesity and its associated conditions." (PMID 40118456, 2025). "Disruptions in the leptin–melanocortin–oxytocin pathway or alterations in energy balance regulation can be consequences of SIM1 mutations contributing to the development of obesity." (PMID 40429924, 2025). "In this study, obesity led to an increased immune aging and enhanced tumor progression by causing T-cell exhaustion through leptin, but paradoxically, obesity enhanced anti-cancer response and improved overall survival of cancer-bearing mice and cancer patients treated with ICIs." (PMID 39516409, 2025). "Living with obesity is associated with leptin and ghrelin resistance and changes to other gut hormones that may increase appetite and contribute to persistence of current obesity." (PMID 39891415, 2025). "While leptin levels are positively associated with obesity and insulin resistance, it remains unclear whether sOB-R and FLI show similar correlations." (PMID 41441006, 2025). "Recent research has demonstrated that long-term activation of ARC AgRP neurons or hypothalamic GABAergic neurons, by specific expression of the Na+ channel NachBac, induces severe obesity and hyperphagia, akin to the phenotypes of leptin-deficient (ob/ob) mice." (PMID 40130157, 2025). "Tumor necrosis factor (TNF), the first pro-inflammatory cytokine produced in the adipose tissue, acts as a catabolic mediator promoting the production of other pro-inflammatory cytokines, adipokines (such as leptin) and chemokines that cause obesity-associated metaflammation." (PMID 39837875, 2025). "The obesity phenotype in leptin- and LepRb-deficient mice is largely recapitulated by LepRb deletion specifically from neurons highlighting the importance of the brain in mediating the metabolic effects of leptin." (PMID 41251447, 2025). "For instance, elevated levels of leptin or low levels of adiponectin in pre‐obese individuals may indicate a higher risk for developing obesity‐related metabolic disorders." (PMID 40551726, 2025). "Moreover, the authors demonstrated additional obesity‐associated factors, such as leptin and insulin, as possible drivers of DNA damage." (PMID 40523654, 2025). "Conversely, overweight and obesity were inversely associated with dementia and AD, which could be partially explained by elevated circulating concentrations of leptin, a hormone secreted by adipose tissue that has been linked to reduced dementia risk." (PMID 41192777, 2025). "Leptin and adiponectin are key adipokines secreted from adipose tissue that regulate energy homeostasis and metabolic response, with an abnormal adiponectin/leptin ratio linked to diseases including obesity." (PMID 40986521, 2025).
Obesity (continued). "In the BAriatric surgery Rijnstate and Radboudumc neuroImaging and Cognition in Obesity (BARICO) cohort study of individuals with severe obesity undergoing Roux-en-Y gastric bypass, substantial postoperative weight loss was accompanied by decreased plasma leptin." (PMID 41516046, 2025). "The directionality of these associations suggests that their downregulation in obesity may contribute directly to endothelial dysfunction, immune dysregulation, and elevated leptin levels." (PMID 40981199, 2025). "Obesity is associated with increased leptin levels and decreased ghrelin and adiponectin levels." (PMID 40137085, 2025). "Obesity is associated with leptin production and high serum leptin concentration." (PMID 41181590, 2025). "Notably, elevated blood leptin levels have been associated with reduced microbiota diversity in both lean individuals and those with obesity." (PMID 40309850, 2025). "Obesity is associated with increased levels of aldosterone and leptin." (PMID 40219007, 2025). "Elevated leptin levels, often associated with obesity, can lead to anovulation in female elephants, and may also impair sperm production in males, as has been observed in humans." (PMID 40646763, 2025). "One key adipokine associated with obesity and pro-inflammatory activity is leptin." (PMID 41154857, 2025). "It has been suggested that a hormonal co-factor—perhaps also fat-derived and inversely associated with fat mass—may be required in the presence of obesity to prevent leptin resistance." (PMID 40214973, 2025). "The discovery of leptin and its receptor genes, along with the leptin‐driven melanocortin 4 signaling pathway, led to investigations into genetic causes of early‐onset severe obesity." (PMID 40551726, 2025). "Furthermore, frequent awakenings and sleep fragmentation affect the regulation of key hormones such as leptin and ghrelin, causing alterations in energy metabolism and increasing the risk of obesity, another factor that enhances insulin resistance." (PMID 40508878, 2025). "Obese (ob/ob) mice are leptin-deficient, and are used as models for type 2 diabetes and obesity." (PMID 40724847, 2025). "Likewise, deactivation of MAPK10 in neurons induces weight gain and alters insulin and leptin signaling, characteristics associated with obesity." (PMID 40140215, 2025). "Most of the identified single-gene mutations are associated with the leptin-melanocortin pathway and may be present in up to 6% of individuals with severe obesity since childhood." (PMID 41373743, 2025). "Given that leptin resistance is closely linked to metabolic dysfunction, obesity, and chronic inflammation, its impact on both JAK-STAT and TGF-β could provide a unifying explanation for the metabolic–immune dysregulation observed in FS." (PMID 40095902, 2025). "According to studies, decreasing sleep duration may raise the risk of weight gain and obesity by upregulating hunger also through a drop in leptin, an increase in ghrelin, and a decrease in insulin sensitivity." (PMID 38778593, 2025). "Elevated levels of leptin may contribute to the hyperthyrotropinemia observed in obesity and may also heighten the risk of developing thyroid autoimmunity, potentially leading to subsequent hypothyroidism." (PMID 39859575, 2025). "Oral supplementation with NMN may be effective at improving obesity and obesity-associated hypertriglyceridemia in obese individuals with low energy expenditure and/or leptin resistance." (PMID 40422909, 2025). "Additionally, it explores the associations of leptin with markers of obesity, glycemic parameters, and insulin resistance to better understand its metabolic implications." (PMID 40630340, 2025). "Monogenic obesity results from homozygous mutations in the leptin-melanocortin system, leading to congenital leptin deficiency characterized by severe obesity with hyperphagia and multiple endocrine disorders such as diabetes mellitus, dyslipidemia, and ovarian dysfunction, among others." (PMID 41013830, 2025).